FGF8 (fibroblast growth factor 8)
Description:
Plays an important role in the regulation of embryonic development, cell proliferation, cell differentiation and cell migration. Required for normal brain, eye, ear and limb development during embryogenesis. Required for normal development of the gonadotropin-releasing hormone (GnRH) neuronal system. Plays a role in neurite outgrowth in hippocampal cells.
Synonyms: FGF-8; AIGF; HBGF-8; HH6; KAL6
Tractability: Antibody: its Gene Ontology location is reachable by antibodies, with high confidence; UniProt places it where antibodies can reach, with medium confidence; UniProt predicts a signal peptide or a membrane-spanning region.
Gene: Protein-coding gene on chromosome 10 (101,770,109 to 101,780,371, reverse strand). Ensembl gene ENSG00000107831.
Subcellular location: Secreted
Pathways (Reactome):
Signal Transduction: Downstream signaling of activated FGFR1; FGFR1c ligand binding and activation; FGFR2c ligand binding and activation; FGFR3b ligand binding and activation; FGFR3c ligand binding and activation; FGFR4 ligand binding and activation; FGFRL1 modulation of FGFR1 signaling; FRS-mediated FGFR1 signaling; FRS-mediated FGFR2 signaling; FRS-mediated FGFR3 signaling; FRS-mediated FGFR4 signaling; Negative regulation of FGFR1 signaling; Negative regulation of FGFR2 signaling; Negative regulation of FGFR3 signaling; Negative regulation of FGFR4 signaling; PI-3K cascade:FGFR1; PI-3K cascade:FGFR2; PI-3K cascade:FGFR3; PI-3K cascade:FGFR4; PI3K Cascade; PI5P, PP2A and IER3 Regulate PI3K/AKT Signaling; PIP3 activates AKT signaling; Phospholipase C-mediated cascade: FGFR1; Phospholipase C-mediated cascade; FGFR2; Phospholipase C-mediated cascade; FGFR3; Phospholipase C-mediated cascade; FGFR4; RAF/MAP kinase cascade; SHC-mediated cascade:FGFR1; SHC-mediated cascade:FGFR2; SHC-mediated cascade:FGFR3; SHC-mediated cascade:FGFR4
Disease: Activated point mutants of FGFR2; Constitutive Signaling by Aberrant PI3K in Cancer; Signaling by FGFR1 in disease; Signaling by FGFR2 in disease; Signaling by FGFR3 in disease; Signaling by activated point mutants of FGFR1; Signaling by activated point mutants of FGFR3
Developmental Biology: Formation of the posterior neural plate; M-decay: degradation of maternal mRNAs by maternally stored factors
Gene Ontology:
Molecular function: growth factor activity; type 1 fibroblast growth factor receptor binding; type 2 fibroblast growth factor receptor binding; chemoattractant activity
Biological process: bone development; dopaminergic neuron differentiation; fibroblast growth factor receptor signaling pathway; gonad development; mesonephros development; metanephros development; negative regulation of cardiac muscle tissue development; neuroepithelial cell differentiation; odontogenesis; anatomical structure morphogenesis; dorsal/ventral pattern formation; epithelial to mesenchymal transition involved in endocardial cushion formation; gastrulation; neurogenesis; outflow tract septum morphogenesis; positive regulation of cell differentiation; positive regulation of cell population proliferation; positive regulation of gene expression; positive regulation of MAPK cascade; regulation of cell migration; central nervous system neuron development; dorsal/ventral axon guidance; forebrain neuron development; motor neuron axon guidance; positive chemotaxis; and 2 more
Cellular component: cytoplasm; extracellular region; external side of plasma membrane
Genetic constraint (gnomAD): Loss-of-function variants: 12 observed, 25.42 expected, observed/expected ratio (o/e) 0.47, 90% interval 0.3 to 0.76. The upper end of that interval is the gene's LOEUF score, 0.76, which puts it in group 3 of 6, group 1 being the genes least tolerant of losing a copy. Missense variants: 271 observed, 320.9 expected, observed/expected ratio (o/e) 0.84, 90% interval 0.76 to 0.93. Synonymous variants: 157 observed, 133.52 expected, observed/expected ratio (o/e) 1.18, 90% interval 1.03 to 1.34.
Gene-disease validity (ClinGen):
ClinGen rates the evidence that FGF8 causes each of these diseases.
congenital heart disease (autosomal dominant): Moderate. A heart disease that is present at birth.
Homologues: Orthologues: chimpanzee FGF8 (100% identical), macaque FGF8 (99% identical), pig FGF8 (99% identical), dog FGF8 (95% identical), mouse Fgf8 (91% identical), rat Fgf8 (90% identical), guinea pig FGF8 (78% identical), tropical clawed frog fgf8 (69% identical), zebrafish fgf8a (65% identical), zebrafish fgf8b (57% identical). Paralogues in human: FGF17 (52% identical), FGF18 (44% identical), FGF20 (21% identical), FGF3 (21% identical), FGF9 (21% identical), FGF6 (20% identical), FGF10 (20% identical), FGF16 (20% identical), FGF13 (19% identical), FGF5 (19% identical), FGF14 (18% identical), FGF4 (18% identical), and 9 more.
Diseases named in the same sentence as FGF8 in open-access papers:
FGF8 is named in the same sentence as 134 diseases in open-access papers, as found by Europe PMC text mining. Sharing a sentence is not in itself a finding about the gene and the disease. The quoted sentences say what the papers report.
prostate carcinoma (27 papers, 2001 to 2024). A carcinoma that arises from epithelial cells of the prostate gland. "As part of its hormone-independent prostate cancer promoting effect, the natural HDAC inhibitor trichostatin A (TSA) increased the transcriptional activity of NF-κB in PC3M prostate cancer cells associated with upregulation of fibrose growth factor FGF8." (PMID 35582529, 2022). "Fibroblast growth factor 8 (FGF8) was recognized as an oncogene, and elevated gene expression in hormonal cancers such as prostate cancer and breast cancer, was associated with a poor prognosis." (PMID 32549787, 2020). "For example, FGF-2 and FGF-8 have been implicated in promoting bone metastasis in renal cell carcinoma and prostate cancer, respectively." (PMID 28968431, 2017). "In clinical prostate cancer, overexpression of FGF8 mRNA was found to be associated with high-grade and late-stage disease." (PMID 12778074, 2003). "The peptide was first implicated in prostate cancer when FGF8 mRNA was found to be expressed in prostate cancer cell lines." (PMID 12778074, 2003). "FGF8 expression appears to be associated with human carcinoma of the prostate since higher levels of FGF8 were detected in malignant prostate disease." (PMID 11953856, 2002). "Some studies have shown the role of FGF8 in the initiation, progression, and development of malignancies and associated its abnormal expression with hormone-responsive cancers, including breast and prostate cancer." (PMID 39309198, 2024). "In prostate cancer, FGF8 overexpression is associated with low patient survival." (PMID 37108717, 2023). "FGF8 is reported to express extensively throughout embryonic development and in many cancers, including breast, ovarian, and prostate cancer, but its expression is much more constrained in normal adult tissues." (PMID 39309198, 2024). "FGF8 is highly expressed during embryonic development and several malignancies such as breast, ovarian, and prostate cancer, whereas, in normal adult tissues, its expression is much more restricted." (PMID 37762545, 2023). "Multiple FGFs have been found elevated in different kinds of tumours, such as FGF2 in leukaemia, lung and breast cancer, FGF8 in breast and prostate cancer, FGF10 in lung cancer, FGF19 in hepatocellular carcinoma (HCC) and TNBC." (PMID 33655556, 2021). "Intriguingly, bone metastases from prostate cancer are positive for FGF8 and its ectopic expression increased the growth of prostate cancer cells as intratibial tumors." (PMID 32824198, 2020). "Nevertheless, upregulation of FGF8 has been described in many tumor types, such as breast cancer, colorectal cancer, prostate cancer, and most interestingly hepatocellular carcinoma." (PMID 32824198, 2020). "Recent data indicate that FGF2 and FGF8 stimulate osteoblasts and modulate bone formation in the presence of cancer cells, which in turn increase prostate cancer growth in bone." (PMID 31217507, 2019). "Data from breast and prostatic cancer cell studies indicate that Fgf8 transcription is, in part, under the regulatory control of androgen signaling through androgen receptors (AR)." (PMID 27200347, 2016). "One major candidate is the androgen receptor (AR), which has been shown to upregulate Fgf8 mRNA in 60–70% of newly diagnosed prostate cancers." (PMID 27200347, 2016). "Previous studies showed that androgen was able to induce the mRNA expression levels of Fgf8 in mouse SC-3 breast and human LNCaP prostate cancer cells." (PMID 27200347, 2016). "For example, FGF-8 can enhance the invasive and migratory capacity of prostate cancer cells in vitro and promote bone metastasis in vivo." (PMID 25473897, 2015). "For example, the overexpression of FGF8 in prostate cancer LNCaP cells and mammary tumor MCF-7 cells enhanced growth and invasion in vitro and promoted tumor growth in vivo." (PMID 25473897, 2015). "More than 80% of prostate cancer cells express FGF8, and the levels of FGF8 expression correlate with the levels of invasiveness." (PMID 23469107, 2013).
prostate carcinoma (continued). "Our results are in line with those of studies on human prostate cancer, where the expression of FGF-8, VEGF and clinicopathological findings correlate with each other." (PMID 21034500, 2010). "FGFR3 binds to multiple FGFs known to be upregulated in human prostate cancer (FGF1, FGF2 and FGF8), and is potentially important in prostate cancer." (PMID 15655558, 2005). "Overexpression of multiple FGFs (namely aFGF/FGFl, bFGF/FGF2, FGF6 and FGF8) has been identified in prostate cancer." (PMID 15655558, 2005). "As both FGF8 mRNA and protein levels are increased in prostate cancer, this points to transcriptional control of the gene as a mechanism of regulating expression." (PMID 12778074, 2003). "Fibroblast growth factor 8 can transform NIH3T3 cells and its expression has been found to be associated with breast and prostate cancer." (PMID 11953856, 2002). "This is in contrast to a prostate cancer report in which higher levels of FGF8 were found in less differentiated cancers." (PMID 11953856, 2002). "In conclusion, we report for the first time a correlation of both tumour and stromal VEGF expression in prostate cancer with clinical parameters as well as its correlation to FGF-8 expression." (PMID 11506499, 2001). "In view of this, we have investigated VEGF expression in 67 cases of prostate cancer previously characterized for fibroblast growth factor-8 (FGF-8) expression." (PMID 11506499, 2001). "However, overexpression of FGF8 in humans occurs in benign breast and prostate lesions, in breast and prostate cancer, and bone metastases in prostate cancer." (PMID 39766329, 2024). "Additionally, as a downstream cell growth regulator, FGF8 can mediate the tumor inhibitory effect of Annexin-A7 in prostate cancer." (PMID 37108717, 2023). "FGF8 has been shown to induce morphological changes, promote anchorage-independent cell proliferation in vitro, and promote tumor growth in vivo in breast and prostate cancer cells." (PMID 37762545, 2023). "Consequently, preclinical testing of a neutralizing antibody to FGF8 significantly inhibited growth of prostate cancer cells in vitro and of mammary tumors in nude mice." (PMID 32824198, 2020). "FGF8 was also found to have a synergistic role with VEGF in prostate cancer." (PMID 30079292, 2018). "The microarray analysis indicated that FGF8 was up regulated by 8.31-fold in prostate cancer tissues compared to BPH tissue which was further confirmed by western blot analysis (2.56 fold over-expressed in cancer tissues, p = 0.001) and immunohistochemistry in the study samples." (PMID 28852180, 2017). "Additionally, Valtaet al found expression of FGF-8 in PC-3 prostate cancer cells increased their growth as intratibial tumors and markedly affected formation of bone lesions in this in vivo model of prostate cancer metastasis." (PMID 25473897, 2015). "Additionally, studies of correlations of VEGF, FGF8 and HIF1 with each other and characteristics of clinical tumour samples and outcome of prostate cancer patients would clarify the role and significance of FGF8 in regulation of prostate cancer progression." (PMID 21034500, 2010). "It remains to be studied whether FGF8 expression is able to contribute to development of resistance to radiation and cytotoxic therapies of prostate cancer." (PMID 21034500, 2010). "FGF8 appeared to be particularly important as paracrine and autocrine factors in prostate cancer." (PMID 15655558, 2005). "However, another group found FGF8 expressed in benign prostatic hypertrophy as well as prostate cancer." (PMID 11953856, 2002). "FGF1, FGF2, FGF6, FGF8, FGF19 and FGF23 are involved in prostate cancer development and progression." (PMID 33655556, 2021). "Consistent with this, the levels of SEF is downregulated, whereas FGF2, FGF8, and FGFR4 levels are upregulated in aggressive prostate cancer specimens." (PMID 23900974, 2013).
prostate carcinoma (continued). "In prostate cancer, FGFR1 and FGFR4 as well as the ligands FGF-1, FGF-2, FGF-6, FGF-8, FGF-9, and FGF-17 are all known to be over-expressed." (PMID 22078327, 2011). "Studies of our own and others on FGF8 have shown that reciprocal FGF/FGF receptor mediated interactions between tumour cells and stromal cells play important roles in prostate cancer progression and angiogenesis." (PMID 21034500, 2010). "For instance, KM1334 neutralizing antibodies targeting the FGF8 isoform b significantly hinder FGF ligand-mediated signaling in mammary tumorigenesis and FGF8b-expressing clinical prostate cancers in addition to, inflammatory responses and bone damages in rat model of rheumatoid arthritis." (PMID 23900974, 2013). "Some investigators have demonstrated an involvement in malignant prostate disease since FGF8 was detected in prostatic cancers, but not in benign prostatic hypertrophy." (PMID 11953856, 2002). "Although immunohistochemical studies have been carried out showing a correlation between the grade of prostate cancers and the amount of FGF8 expression, such extensive studies have not previously been carried out using human breast tissue." (PMID 11953856, 2002). "Finally, heat map analysis showed that prostate cancer and BPH tissues may be distinguished on the basis of the expression of the genes such as FKBP4, FGF8, c-Myc in addition to cyclinD1, CDK4, Ki-67 and p21." (PMID 28852180, 2017). "Unfortunately, no prostate cancer cell line expressing FGF8 is available." (PMID 21034500, 2010).
breast cancer (15 papers, 2002 to 2024). A primary or metastatic malignant neoplasm involving the breast. "FGF8 has recently been linked to tumor progression in clinical samples from patients with prostate and breast cancer." (PMID 39309198, 2024). "High levels of FGF8 expression in clinical samples is associated with tumor progression and a poor prognosis in several cancers, including prostate and breast cancer." (PMID 25473897, 2015). "mRNA encoding FGF8 mRNA has been found expressed in the epithelial cells of breast cancer using in situ hybridisation and we find a similar expression pattern in the epithelial component of normal and malignant breast tissue." (PMID 11953856, 2002). "A study showed that overexpressed FGF8 in mouse mammary cancer cells led to EMT, anchorage-independent growth, and faster tumor growth in vivo." (PMID 39309198, 2024). "When first discovered, FGF8 was known as an androgen-induced growth factor released by a breast cancer cell line." (PMID 37762545, 2023). "As the canonical FGF8 receptors FGFR2c and FGFR3c are expressed at low level in breast cancer cells, it is possible that FGF8 acts in an autocrine manner on FGFR1 and FGFR4, which are instead present in the breast epithelium." (PMID 35193394, 2022). "It has been reported that one of the FGF8 isoforms, FGF8b, increases anchorage-independent growth in vitro and vascularization in nude mice, suggesting that FGF8 is involved in the induction of transformation and in angiogenesis in breast cancer." (PMID 35193394, 2022). "FGF8 was originally referred to as androgen-induced growth factor (AIGF) as it played a role in the growth of androgen-dependent growth of mouse mammary tumor cell line." (PMID 30079292, 2018). "In prostate and breast cancer, the overexpression of FGF8 is correlated with advanced tumor stage and shorter survival times." (PMID 25473897, 2015). "Engineered overexpression of FGF8 in both prostate and breast cancer cell lines has been shown to be tumor promoting in many in vitro and in vivo studies." (PMID 25473897, 2015). "In mouse mammary tumor cells, overexpression of FGF8 can induce EMT and anchorage independent growth in vitro and accelerated tumor growth in vivo." (PMID 25473897, 2015). "FGF8 was originally identified as an androgen-induced growth factor from the conditioned medium of the mouse mammary carcinoma cell line SC-3." (PMID 25473897, 2015). "Fibroblast growth factor-8 (FGF8), originally cloned from an androgen-dependent mouse mammary carcinoma cell line, belongs to the angiogenic FGF family." (PMID 25912421, 2015). "Fibroblast growth factor 8 was originally cloned from conditioned medium of mouse mammary tumour-derived SC-3 cells and was identified as androgen-induced growth factor (AIGF)." (PMID 21034500, 2010). "FGF8 was originally isolated from the conditioned medium of an androgen-dependent mouse mammary tumor cell line (SC-3) as an androgen-induced growth factor, and was later classified as a member of the FGF family based on structural similarity." (PMID 18699993, 2008). "We find low levels of FGF8 in normal breast epithelial cells and the level of staining appears to be increased in some breast cancers." (PMID 11953856, 2002). "We have previously reported that FGF8 mRNA is expressed at a higher level in breast cancer cells than in normal breast epithelial cells." (PMID 11953856, 2002). "The Grade I breast carcinoma specimens showed similar low expression of FGF8 as normal breast tissues but statistical comparative analysis with higher tumour grades was not possible as numbers were small." (PMID 11953856, 2002). "FGF8 is of potential interest in breast biology since it was first isolated from a mouse mammary carcinoma cell line and its expression is regulated by steroid hormones; in particular dihydroxytestosterone." (PMID 11953856, 2002).